INSYN2A (inhibitory synaptic factor 2A)
Description:
Component of the protein machinery at the inhibitory synapses, probably acting as a scaffold. Inhibitory synapses dampen neuronal activity through postsynaptic hyperpolarization. This synaptic inhibition is fundamental for the functioning of the central nervous system, shaping and orchestrating the flow of information through neuronal networks to generate a precise neural code.
Synonyms: InSyn2; C10orf141; FAM196A; FLJ45557
Tractability: No criterion of Open Targets' tractability assessment is met for any kind of drug.
Gene: Protein-coding gene on chromosome 10 (127,135,426 to 127,196,591, reverse strand). Ensembl gene ENSG00000188916.
Subcellular location: Postsynaptic density
Gene Ontology:
Molecular function: protein binding
Biological process: inhibitory postsynaptic potential
Cellular component: postsynaptic density
Genetic constraint (gnomAD): Loss-of-function variants: 17 observed, 38.93 expected, observed/expected ratio (o/e) 0.44, 90% interval 0.3 to 0.65. The upper end of that interval is the gene's LOEUF score, 0.65, which puts it in group 2 of 6, group 1 being the genes least tolerant of losing a copy. Missense variants: 591 observed, 651.22 expected, observed/expected ratio (o/e) 0.91, 90% interval 0.85 to 0.97. Synonymous variants: 255 observed, 274.33 expected, observed/expected ratio (o/e) 0.93, 90% interval 0.84 to 1.03.
Homologues: Orthologues: chimpanzee INSYN2A (99% identical), macaque INSYN2A (96% identical), mouse Insyn2a (84% identical), rat Insyn2a (82% identical), guinea pig INSYN2A (81% identical), pig INSYN2A (80% identical), rabbit INSYN2A (74% identical), dog INSYN2A (73% identical), tropical clawed frog insyn2a (61% identical), zebrafish INSYN2A (49% identical), zebrafish insyn2ab (43% identical). Paralogues in human: INSYN2B (23% identical).
Diseases named in the same sentence as INSYN2A in open-access papers:
INSYN2A is named in the same sentence as 1 disease in open-access papers, as found by Europe PMC text mining. Sharing a sentence is not in itself a finding about the gene and the disease.
INSYN2A shares sentences with these, for which no sentence is quoted: tumor (1 paper).